HIRA (histone cell cycle regulator)
Description:
Cooperates with ASF1A to promote replication-independent chromatin assembly. Required for the periodic repression of histone gene transcription during the cell cycle. Required for the formation of senescence-associated heterochromatin foci (SAHF) and efficient senescence-associated cell cycle exit.
Synonyms: DGCR1; TUPLE1; TUP1
Tractability: PROTAC: UniProt records ubiquitination sites on it; ubiquitination databases record sites on it; its protein half-life has been measured.
Gene: Protein-coding gene on chromosome 22 (19,330,693 to 19,447,450, reverse strand). Ensembl gene ENSG00000100084.
Subcellular location: Nucleus; Nucleus, PML body
Subcellular location (Human Protein Atlas): Nucleoplasm
Pathways (Reactome):
Cellular responses to stimuli: Formation of Senescence-Associated Heterochromatin Foci (SAHF)
Developmental Biology: Replacement of protamines by nucleosomes in the male pronucleus
Gene Ontology:
Molecular function: histone binding; protein binding; RNA polymerase II-specific DNA-binding transcription factor binding; nucleosome binding; transcription corepressor activity
Biological process: transcription elongation-coupled chromatin remodeling; anatomical structure morphogenesis; nucleosome assembly; regulation of chromatin organization; regulation of transcription by RNA polymerase II; chromatin organization; chromatin remodeling; DNA-templated transcription; negative regulation of DNA-templated transcription; regulation of DNA-templated transcription
Cellular component: chromatin; extracellular exosome; HIR complex; nucleoplasm; protein-containing complex; nucleus; PML body
Genetic constraint (gnomAD): Loss-of-function variants: 11 observed, 103.58 expected, observed/expected ratio (o/e) 0.11, 90% interval 0.066 to 0.18. The upper end of that interval is the gene's LOEUF score, 0.18, which puts it in group 1 of 6, group 1 being the genes least tolerant of losing a copy. Missense variants: 756 observed, 1,210 expected, observed/expected ratio (o/e) 0.62, 90% interval 0.59 to 0.66. Synonymous variants: 479 observed, 497.61 expected, observed/expected ratio (o/e) 0.96, 90% interval 0.89 to 1.04.
Homologues: Orthologues: chimpanzee HIRA (99% identical), guinea pig HIRA (97% identical), mouse Hira (96% identical), rat Hira (95% identical), macaque HIRA (94% identical), dog HIRA (91% identical), rabbit HIRA (90% identical), pig HIRA (87% identical), tropical clawed frog hira (78% identical), zebrafish hira (70% identical), Drosophila melanogaster Hira (36% identical), Caenorhabditis elegans hira-1 (26% identical).
Diseases named in the same sentence as HIRA in open-access papers:
HIRA is named in the same sentence as 49 diseases in open-access papers, as found by Europe PMC text mining. Sharing a sentence is not in itself a finding about the gene and the disease. The quoted sentences say what the papers report.
DiGeorge syndrome (7 papers, 2016 to 2023). "In the pathological context, HIRA was initially associated with DiGeorge syndrome, as the HIRA gene lies within the q11 region of chromosome 22, which is deleted in these patients." (PMID 28284043, 2017). "Clinically, the HIRA gene is of interest because it lies within the critical region associated with 22q11.2 deletion syndrome (DiGeorge and velocardiofacial syndromes; OMIM 188400)." (PMID 26935106, 2016). "HIRA encodes a histone chaperone and is considered the primary candidate gene in DiGeorge syndrome." (PMID 35361250, 2022). "Individuals with 22q11.2 deletion syndrome (DiGeorge and velocardiofacial syndromes) are heterozygous for a genomic deletion that includes the HIRA gene." (PMID 26935106, 2016). "This is particularly intriguing because human HIRA was originally identified through the study of DiGeorge syndrome patients, who commonly have heart and brain abnormalities, arising from a deletion of the q11 cytogenetic band of chromosome 22, which contains the HIRA gene." (PMID 29479426, 2018). "Genes that may influence the phenotype may be similar to genes involved in the same deleted region in DiGeorge syndrome (DGS; OMIM 188400) and velocardiofacial syndrome (VCFS; OMIM 192430) (mainly TBX1, HIRA, CRKL)." (PMID 36226175, 2022).
viral infection (6 papers, 2017 to 2025). "HIRA has previously been shown to localize to PML-NBs during viral infection, cellular senescence or after interferon treatment and here we show that this localization can also be promoted by keratinocyte differentiation." (PMID 41019635, 2025). "HIRA is normally distributed throughout the nucleus, but under conditions of stress (such as viral infection, senescence, or interferon treatment) it is observed at PML-NBs." (PMID 41019635, 2025). "The histone chaperone, HIRA localizes to PML-NBs in response to viral infection or transfection with plasmid DNA, both of which induce secretion of IFNs." (PMID 40568077, 2025). "In order to investigate the role of HIRA in the regulation of intracellular immunity during virus infection, we conducted RNA-seq analysis in HSV-1 infected cells depleted of HIRA." (PMID 30901352, 2019). "Our study highlights the importance of histone chaperones in the coordinated regulation of multiple phases of host immunity in response to pathogen invasion and identifies a key role for HIRA in the induction of innate immunity to virus infection." (PMID 30901352, 2019). "Similar dual anti-viral and pro-viral effects have recently been reported for PML, and the H3.3-specific chaperone, HIRA, has been shown to both enhance and restrict viral infection depending on context." (PMID 30465651, 2018). "In sum, these results, in cell culture and a mouse model, demonstrate a role of histone chaperone HIRA in sensing incoming foreign DNAs, suppression of viral gene expression and productive viral infection both in vitro and in vivo." (PMID 28981850, 2017). "Daxx is constitutively associated with PML-NBs, while the histone H3.3 chaperone HIRA only associates with PML-NBs in response to cellular senescence, interferon (IFN) stimulation, and viral infection." (PMID 40568077, 2025). "These latter events underscore a role of HIRA in intrinsic anti-viral defense via chromatinization of incoming viral genomes as well as stimulation of innate immune defenses in the case of viral infection." (PMID 37227756, 2023). "While the histone chaperones HIRA and ASF1A have been implicated in the initial loading of histones onto HSV DNA during the first few hours of infection, these reports also demonstrated that HIRA and ASF1A actually promote productive viral infection." (PMID 30465651, 2018). "The H3.3 histone chaperone complex HIRA accumulates in PML NBs upon senescence, viral infection or IFN-I treatment in primary cells." (PMID 37227756, 2023). "ChIP-seq analysis revealed that PML, the principle scaffolding protein of PML-NBs, was required for the enrichment of HIRA onto ISGs, identifying a role for PML in the HIRA-dependent regulation of innate immunity to virus infection." (PMID 30901352, 2019). "Similar to previous studies, we observed that IFN treatment caused re-localization of HIRA to PML-NBs in NIKS keratinocytes and this is independent of viral infection or cellular senescence." (PMID 40568077, 2025). "While senescence was the first stress shown to induce accumulation of HIRA complex in PML NBs, IFN-I signaling pathway was recently shown to be responsible for similar behavior of HIRA upon a viral infection." (PMID 37227756, 2023).
Alpha-thalassemia (3 papers, 2020 to 2023). Alpha-thalassemia is an inherited hemoglobinopathy characterized by impaired synthesis of alpha-globin chains leading to a variable clinical picture depending on the number of affected alleles. "We consider four key protein complexes: chromatin assembly factor 1 (CAF-1) complex, histone regulator A (HIRA) complex, death domain-associated and alpha-thalassemia/mental retardation, X-linked protein (DAXX/ATRX) complex, and Holliday junction recognition protein (HJURP) complex (top row)." (PMID 37734377, 2023). "The four different residues in the core domain are critical for the recognition of H3.3 by dedicated protein chaperones: the histone cell cycle regulator (HIRA) and the death domain associated protein/alpha thalassemia/mental retardation syndrome X-linked (DAXX/ATRX) complexes." (PMID 33353064, 2020).
breast carcinoma (3 papers, 2020 to 2023). "We demonstrate that nuclear PHB interacts with HIRA and stabilizes HIRA complex components, enabling it to regulate metastasis in breast cancer by H3.3 deposition at mesenchymal marker promoters." (PMID 32865342, 2020). "PHB participates in and stabilizes an important epigenetic chaperone HIRA complex in breast cancer cells." (PMID 32865342, 2020). "Similarly, in a metastasis-induced breast cancer model, a pronounced upregulation of HIRA and a decrease of CAF-1 can be observed." (PMID 35087762, 2021). "We further confirmed that knockdown of PHB reduced the protein level of EMT markers VIMENTIN and FIBRONECTIN and inhibited the migration of the MDA‐ MB‐231 breast cancer cell line which supports the important role of PHB‐involved HIRA complex in increasing mesenchymal gene expression." (PMID 32865342, 2020). "Accordingly, overexpression of nuclear PHB upregulates the HIRA complex‐controlled H3.3 enrichment and increases the level of mesenchymal markers and finally induces the EMT in breast cancer." (PMID 32865342, 2020). "We showed PHB participates in the HIRA complex by interacting with HIRA through the linker region of the PHB domain and stabilizes all components of the HIRA complex in breast cancer." (PMID 32865342, 2020). "Additionally, we first reported that PHB interacted with HIRA through the linker region of the PHB domain and stabilized all the components of HIRA complexes in breast cancer." (PMID 32865342, 2020).
colon cancer (3 papers, 2018 to 2019). "Western blot analysis in cell lines of CML (K562) and AML (HL60) origin along with a colon cancer cell line (other than hematopoietic or lymphoid origin) demonstrated enhanced level of HIRA in CML cell line." (PMID 32123848, 2019). "Here, we report that in human colon cancer cells, the H3.3 chaperones HIRA and DAXX promote ectopic CENP-A deposition." (PMID 30365520, 2018).
herpesvirus infection (3 papers, 2017 to 2022). "Our research uncovers distinct kinetics in the spatiotemporal recruitment of HIRA to infecting viral genomes and PML-NBs during different phases of HSV-1 infection and identifies dual roles for HIRA in the sequential regulation of intrinsic and innate immunity to herpesvirus infection." (PMID 30901352, 2019). "As herpesvirus genomes enter the nucleus as naked DNA, we asked whether the HIRA chaperone complex affects herpesvirus infection." (PMID 28981850, 2017). "Importantly, none of these hypothesises are mutually exclusive and further studies are required to identify the role(s) of PML and PML-NBs in the HIRA-dependent induction of ISG expression during herpesvirus infection." (PMID 30901352, 2019). "Finally, we asked whether HIRA suppressed viral replication during herpesvirus infection in vivo." (PMID 28981850, 2017). "Here we report that HIRA displays spatiotemporally distinct kinetics of recruitment to infecting HSV-1 genomes and PML-NBs, which independently contribute to the regulation of intrinsic and innate immune defences in response to herpesvirus infection." (PMID 30901352, 2019). "Recent studies have shown that the HIRA (histone cell cycle regulator) histone H3.3 chaperone complex, composed of HIRA, Ubinuclein 1 (UBN1), and Calcineurin-binding protein 1 (CABIN1), relocalizes to PML-NBs in response to replication-defective herpesvirus infection." (PMID 30901352, 2019). "Moreover, another histone H3.3 chaperone, histone cell cycle regulator (HIRA), that has been shown to localize to PML-NBs upon herpesvirus infection as well as IFN stimulation has recently also been identified to contribute to both intrinsic and innate immune responses." (PMID 35939517, 2022).
congenital heart disease (2 papers, 2018 to 2024). A heart disease that is present at birth. "Recently, HIRA was found to be one of 46 chromatin modifiers that had a significant loss of function mutation (p value = 0.03) in a large congenital heart disease cohort study." (PMID 30030774, 2018). "Loss of function mutation in HIRA, together with other chromatin modifiers, was found in patients with congenital heart diseases." (PMID 30030774, 2018).
heart failure (2 papers, 2016). Inability of the heart to pump blood at an adequate rate to meet tissue metabolic requirements. "Based on the known cellular processes for which HIRA's functions are important, there are several potential mechanisms underlying heart failure in the Hira CKO." (PMID 26935106, 2016). "Although Hira heterozygous mice are phenotypically normal with no apparent congenital heart defects, cardiomyopathy and heart failure resulting from total loss of HIRA in cardiomyocytes gives insight into the pathways affected by reduction in HIRA in individuals with 22q11.2." (PMID 26935106, 2016).
leukemia (2 papers, 2019 to 2026). A malignant (clonal) hematologic disorder, involving hematopoietic stem cells and characterized by the presence of primitive or atypical myeloid or lymphoid cells in the bone marrow and the blood. "Downregulation of HIRA in K562 cells displayed cell cycle arrest, loss in proliferation, presence of polyploidy with significant increase in CD41+ population thereby limiting proliferation but inducing differentiation of leukemia cells to megakaryocyte fate." (PMID 32123848, 2019). "So, we thought that our understanding of normal hematopoiesis as a function of HIRA could also form the basis in understanding the abnormal hematopoiesis prevalent in leukemia." (PMID 32123848, 2019). "Based on our initial observation of HIRA‐mediated regulation of RUNX1 in hematopoiesis, we were intrigued to investigate whether this phenomenon could be relevant in leukemia cells." (PMID 32123848, 2019).
promyelocytic leukaemia (2 papers, 2013 to 2019). "Here we show that the histone H3.3 chaperone HIRA (histone cell cycle regulator) associates with promyelocytic leukaemia nuclear bodies (PML-NBs) to stimulate the induction of innate immune defences against herpes simplex virus 1 (HSV-1) infection." (PMID 30901352, 2019).
Tetralogy of Fallot (2 papers, 2016 to 2018). A congenital cardiac malformation comprising pulmonary stenosis, overriding aorta, ventricular septum defect, and right ventricular hypertrophy. "However, to our knowledge, no mutations of HIRA have been described in exome sequencing analyses of patients with congenital heart defect, although one study of a Chinese cohort discovered a genetic association between a variant in the 3’ UTR region of HIRA and the diagnosis of tetralogy of Fallot." (PMID 27518902, 2016).
anaemia (1 paper, 2021). "Other authors analysed hematopoietic cells with specific HIRA deletion in mice and showed that this dramatically reduces bone marrow hematopoietic stem cells (HSCs), resulting in anaemia, thrombocytopenia and lymphocytopenia." (PMID 34445317, 2021).
colorectal cancer (1 paper, 2023). A primary or metastatic malignant neoplasm that affects the colon or rectum. "We have shown previously that the H3.3 chaperone HIRA prevents CENP-A mislocalization in budding yeast, and similar observations have been reported in the colorectal cancer cell line SW480." (PMID 37129573, 2023).
cutaneous melanoma (1 paper, 2024). A primary melanoma arising from atypical melanocytes in the skin. "The second most recurrently altered TAD boundary in our cutaneous melanoma cohort affected the NER genes HIRA and DGCR8, which are involved in the repair of mutations caused by UV mutagenesis." (PMID 38758740, 2024). "Other than MTAP and SEPTIN5, CDKN2A, CDKN2B, HIRA, and DGCR8 were the only recurrently altered cutaneous melanoma genes that were not recurrently altered in acral or mucosal melanomas, which frequently lack the presence of UV-induced mutations." (PMID 38758740, 2024).
heart defects (1 paper, 2016). "The HIRA gene lies within the 22q11.2 deletion syndrome critical region; individuals with this syndrome have multiple congenital heart defects." (PMID 26935106, 2016).
immune deficiency (1 paper, 2022). "This deletion does not affect the DGS critical genes HIRA and TBX1; however, immune deficiency and recurrent infections have been described for this region." (PMID 35486341, 2022).
Infertility (1 paper, 2018). "In our study, mutations in the HIRA SNPs, g.71874104G>A and g.71833755T>C, did not cause infertility in ewes." (PMID 29734691, 2018).
Insulin resistance (1 paper, 2025). Increased resistance towards insulin, that is, diminished effectiveness of insulin in reducing blood glucose levels. "Taken together, these data indicate that HIRA is important for glucose homeostasis and that deletion of Hira in adipocytes causes insulin resistance in mice." (PMID 40196683, 2025).
latent infection (1 paper, 2021). "HIRA complex colocalizes with the PML-NBs in senescent cells, and during HSV-1 latent infection, HIRA is involved in the repression of the viral genome." (PMID 34208020, 2021).
Obesity (1 paper, 2025). Accumulation of substantial excess body fat. "Our findings not only identify HIRA as an epigenomic regulator of insulin sensitivity, lipogenesis, and obesity-associated adipose expansion, but also reveal a novel mechanism by which HIRA regulates transcription." (PMID 40196683, 2025). "By tissue-specific gene KO in mice, we identify the histone chaperone HIRA as a novel epigenomic regulator of insulin sensitivity and obesity-associated adipose tissue expansion." (PMID 40196683, 2025). "Here we show that tissue-specific knockout of histone chaperone HIRA in mice impairs insulin sensitivity and alleviates adipose tissue expansion during high-fat diet-induced obesity, but only moderately affects embryonic development of adipose tissue." (PMID 40196683, 2025).
prostate carcinoma (1 paper, 2023). A carcinoma that arises from epithelial cells of the prostate gland. "Exploring the function of H3.3 in prostate cancer (PC), we found that knockout (KO) of H3.3 chaperone HIRA suppresses PC growth in vitro and in xenograft settings, deregulates androgen-induced gene expression and alters androgen receptor (AR) binding within enhancers of target genes." (PMID 37638746, 2023).
renal fibrosis (1 paper, 2018). A final common manifestation of a wide variety of chronic kidney diseases characterized by glomerulosclerosis and tubulointerstitial fibrosis. "Taken together, our data from UUO mice, rat kidney cells and human biopsy samples indicate that histone H3.3 and HIRA are implicated in TGF-β1-induced renal fibrosis." (PMID 30232404, 2018). "First, expression of histone H3.3 and HIRA increases in a mouse model of renal fibrosis induced by UUO." (PMID 30232404, 2018). "However, from the data presented here, we suggest that inhibition of HIRA is a promising therapeutic strategy for the treatment of renal fibrosis." (PMID 30232404, 2018). "Although we showed that inhibition of HIRA expression suppresses TGF-β1-induced α-SMA expression in tubular epithelial cells, the role of HIRA in the progression of renal fibrosis in vivo remains unclear." (PMID 30232404, 2018).
Ureteral obstruction (1 paper, 2018). Obstruction of the flow of urine through the ureter. "In this study, we assessed the roles of histone H3.3 and HIRA in unilateral ureteral-obstruction (UUO) mice." (PMID 30232404, 2018).